PTGER4 (prostaglandin E receptor 4)
Description:
Receptor for prostaglandin E2 (PGE2). The activity of this receptor is mediated by G(s) proteins that stimulate adenylate cyclase. Has a relaxing effect on smooth muscle. May play an important role in regulating renal hemodynamics, intestinal epithelial transport, adrenal aldosterone secretion, and uterine function.
Synonyms: EP4; EP4R
Tractability: Small molecule: an approved drug acts on it; a structure with a bound ligand is known; a high-quality ligand is known; it belongs to a druggable protein family. Antibody: its Gene Ontology location is reachable by antibodies, with high confidence; UniProt places it where antibodies can reach, with medium confidence; UniProt predicts a signal peptide or a membrane-spanning region. PROTAC: ubiquitination databases record sites on it; a small molecule that binds it is known.
Target class: Lipid-like ligand receptor (family A GPCR); Membrane receptor; Prostanoid receptor; Small molecule receptor (family A GPCR); Family A G protein-coupled receptor
Chemical probes: CHEMBL3115074 (high quality), MK-2894 (high quality)
Gene: Protein-coding gene on chromosome 5 (40,679,915 to 40,693,735, forward strand). Ensembl gene ENSG00000171522.
Subcellular location: Cell membrane
Pathways (Reactome):
Signal Transduction: G alpha (s) signalling events; Prostanoid ligand receptors
Gene Ontology:
Molecular function: prostaglandin E receptor activity; protein binding; G protein-coupled receptor activity; prostaglandin receptor activity
Biological process: adenylate cyclase-activating G protein-coupled receptor signaling pathway; adenylate cyclase-inhibiting G protein-coupled receptor signaling pathway; adenylate cyclase-modulating G protein-coupled receptor signaling pathway; immune response; negative regulation of eosinophil extravasation; negative regulation of inflammatory response; negative regulation of integrin activation; response to mechanical stimulus; response to prostaglandin E; bone development; cellular response to mechanical stimulus; cellular response to prostaglandin E stimulus; ERK1 and ERK2 cascade; inflammatory response; JNK cascade; negative regulation of cytokine production; positive regulation of cytokine production; positive regulation of cytosolic calcium ion concentration; positive regulation of inflammatory response; regulation of stress fiber assembly; T-helper cell differentiation; G protein-coupled receptor signaling pathway; response to lipid
Cellular component: plasma membrane; membrane
Genetic constraint (gnomAD): Loss-of-function variants: 11 observed, 33.36 expected, observed/expected ratio (o/e) 0.33, 90% interval 0.21 to 0.55. The upper end of that interval is the gene's LOEUF score, 0.55, which puts it in group 2 of 6, group 1 being the genes least tolerant of losing a copy. Missense variants: 481 observed, 660.67 expected, observed/expected ratio (o/e) 0.73, 90% interval 0.68 to 0.79. Synonymous variants: 275 observed, 288.23 expected, observed/expected ratio (o/e) 0.95, 90% interval 0.86 to 1.05.
Homologues: Orthologues: chimpanzee PTGER4 (99% identical), macaque PTGER4 (98% identical), dog PTGER4 (91% identical), rabbit PTGER4 (91% identical), pig PTGER4 (90% identical), guinea pig PTGER4 (89% identical), rat Ptger4 (89% identical), mouse Ptger4 (88% identical), tropical clawed frog ptger4 (67% identical), zebrafish ptger4b (57% identical), zebrafish ptger4a (54% identical). Paralogues in human: PTGIR (26% identical), PTGER2 (24% identical), PTGDR (23% identical), PTGER1 (20% identical), PTGER3 (19% identical), PTGFR (18% identical), TBXA2R (17% identical).
Diseases named in the same sentence as PTGER4 in open-access papers:
PTGER4 is named in the same sentence as 263 diseases in open-access papers, as found by Europe PMC text mining. Sharing a sentence is not in itself a finding about the gene and the disease. The quoted sentences say what the papers report.
breast cancer (51 papers, 2006 to 2025). A primary or metastatic malignant neoplasm involving the breast. "PTGIS, PTGES, and PTGER4 up-regulation in the group of responders with HER2-positive breast cancer, known by its aggressive behavior, is associated with complete tumor response to treatment with fluorouracil, epirubicin, and cyclophosphamide (FEC)." (PMID 35453789, 2022). "The loss of methylation and activation of PTGER4 can explain the acquisition of endocrine therapy resistance and is a therapeutic target for breast cancer." (PMID 31969157, 2020). "Finally, we analyzed the association between IL-6, PTGER2, and PTGER4 overexpression and breast cancer subtype; hormone receptor status; and distant metastasis-free or overall survival." (PMID 31014367, 2019). "PTGER4 encodes EP4R (prostaglandin E receptor 4) which is the antagonism to inhibit cell growth, proliferation, and metastasis of breast cancer cells; in particular, PTGER4 regulates the aggressive phenotypes of inflammatory breast cancer cells." (PMID 24069348, 2013). "The TME analysis on day 9 after implantation demonstrated that Ptger4-overexpressing mammary tumors had significantly reduced counts of immune cells compared with the controls, confirming the role of tumor cell–intrinsic EP4 signaling in suppressing antitumor immunity and promoting tumor growth." (PMID 39298269, 2024). "The control and Ptger4-overexpressing mammary tumor cells grew at the same rate in vitro." (PMID 39298269, 2024). "PGE2 may also induces cell migration and invasion by upregulation of matrix metalloproteinase 2 (MMP2) via an ERK-ETS1 cascade in pancreatic cancer cell lines and upregulation of CCR7 via PTGER2 (EP2) and PTGER4 (EP4) in breast cancer cell lines." (PMID 24213116, 2011). "Moreover antagonism of PTGER4 signalling with small molecule receptor antagonists or RNA interference has been shown to inhibit cell growth, proliferation, invasion and metastasis of breast cancer cells." (PMID 21589857, 2011). "Two mammary tumor cell lines, PY8119 and E0771, were similar in terms of the absence of Ptger2 expression but showed quite different levels of Ptger4, with E0771 being almost completely deprived of the receptor expression." (PMID 39298269, 2024). "Next, we sought to further test the role of tumor cell EP4 signaling by overexpressing it on a mammary tumor cell line with no endogenous Ptger4 expression." (PMID 39298269, 2024).
lung carcinoma (35 papers, 2007 to 2025). "Short stature homeobox gene two (SHOX2), RAS association domain family 1A (RASSF1A), and prostaglandin E receptor 4 gene (PTGER4) methylation has been reported to be closely related to lung cancer diagnosis and prognosis." (PMID 35634444, 2022). "The methylation analysis of SHOX2, RASSF1A, and PTGER4 panel in plasma showed an efficient diagnostic ability in lung cancer diagnosis." (PMID 34408226, 2021). "NPV and PPV values show that the SHOX2, RASSF1A, and PTGER4 methylation detection of plasma could be an effective complementary tool in high-risk lung cancer diagnosis." (PMID 34408226, 2021). "Biomarkers of DNA methylation such as SHOX2, RASSF1A and PTGER4 can be detected during the early stages of lung cancer, achieving both high sensitivity and specificity." (PMID 40666096, 2025). "Greatly, a diagnostic kit that targets SHOX2 and PTGER4 using MethyLight technology has received FDA approval, offering a novel method for the early detection of lung cancer." (PMID 40666096, 2025). "For instance, the DNA methylation status of SHOX2/PTGER4 in plasma were proved to be valuable biomarkers for diagnosing lung cancer, and had been practically applied in clinical settings." (PMID 41341575, 2025). "A validation study demonstrated that the combined SHOX2 and PTGER4 methylation assay is capable of effectively distinguishing lung cancer patients from healthy individuals." (PMID 40666096, 2025). "Prostaglandin E2 (PGE2) is the most abundant prostaglandin found in lung cancer, and PTGER4 is one of its receptors." (PMID 40666096, 2025). "Various studies have devised methylation biomarkers for diverse cancers like lung, colorectal, cervical, and bladder cancers, which find application in clinical diagnosis, such as the three-gene methylation biomarker (SHOX2/RASSF1A/PTGER4) for lung cancer." (PMID 38680421, 2024). "The results demonstrated that, at a fixed specificity of 90%, the sensitivity of SHOX2 and PTGER4 methylation in plasma for lung cancer was 67%." (PMID 38429660, 2024). "For instance, the hypermethylation of Prostaglandin E Receptor 4 (PTGER4) in the plasma was shown to distinguish patients with lung cancer from those with COPD or benign lung lesions." (PMID 36769181, 2023). "The combined detection of SHOX2, RASSF1A and PTGER4 gene methylation in plasma improved detection sensitivity in lung cancer diagnosis compared to previous studies, and achieved high sensitivity across all histological subtypes of lung cancer." (PMID 34408226, 2021). "Short stature homeobox gene two (SHOX2), ras association domain family 1A (RASSF1A), and prostaglandin E receptor 4 gene (PTGER4) methylation has been separately reported to be highly correlated with lung cancer diagnosis and prognosis." (PMID 34408226, 2021). "As the hypermethylated markers, CDO1 and PTGER4 were detected using plasma and sputum samples in early-stage lung cancers." (PMID 34620221, 2021). "The data showed that the sensitivity of the SHOX2, RASSF1A and PTGER4 methylation panel in blood plasma was 87.0% in lung cancer group." (PMID 34408226, 2021). "The performance of SHOX2/PTGER4 biomarkers to detect lung cancer in plasma samples was initially tested in the study that included 118 lung cancer patients, covering all major histological types and a broad range of stages and 212 healthy controls." (PMID 32631437, 2020). "The blood levels of individual biomarkers [IDH1, DNA methylation of short stature homeobox 2 gene (SHOX2), and prostaglandin E receptor 4 gene (PTGER4)] were measured and statistically analyzed in samples from healthy controls and patients with lung cancer." (PMID 31888670, 2019). "The combination of single biomarkers with high stage-specificity and histological type specificity (SHOX2 and PTGER4 DNA methylation and IDH1) showed better diagnostic performance in the detection of lung cancers compared with single marker assessment." (PMID 31888670, 2019).
lung carcinoma (continued). "Although, the discriminative ability in detection of lung cancers of the SHOX2/PTGER4 DNA methylation marker panel has been confirmed." (PMID 31888670, 2019). "We identified 7 DMRs corresponding to 7 differentially methylated genes (DMGs) including HOXB4, HOXA7, HOXD8, ITGA4, ZNF808, PTGER4, and B3GNTL1 that were highly associated with lung cancer by comparing the methylation profiles of lung cancer and benign nodule tissue." (PMID 37101220, 2023). "Prostaglandin E receptor 4 gene (PTGER4), ras association domain family 1A (RASSF1A), and short stature homeobox gene two (SHOX2) methylation have been separately identified as valuable biomarkers for lung cancer diagnosis in several research studies." (PMID 33691657, 2021). "Notably, the SHOX2, RASSF1A, and PTGER4 methylation panel in plasma achieved a high sensitivity of 82.5% in stage I and 90.5% in stage II lung cancer patients, respectively." (PMID 34408226, 2021). "For instance, in lung cancer patients, the methylation of SHOX2/PTGER4/RASSF1A in plasma DNA has been employed as a biological marker for identifying lung cancer and has found practical applications in clinical settings." (PMID 38680421, 2024). "It turned out that the expressions of B3GNTL1 and HOXD8 were significantly upregulated, while the expression of remaining five genes (HOXB4, ZNF808, ITGA4, PTGER4, and HOXA7) were significantly downregulated in lung cancer tissues (p < 0.01)." (PMID 37101220, 2023). "The Epi proLung assay can be used to detect lung cancer by the determination of the methylation status of the short stature homeobox 2 (SHOX2) and the prostaglandin E receptor 4 (PTGER4) gene." (PMID 33918147, 2021). "Among them, PTGER4, RASSF1A, and SHOX2 methylation biomarkers showed high potential in the diagnosis and prognosis of lung cancer." (PMID 33691657, 2021). "In 2017, the Epi proLung® blood-based version for the lung cancer test received the CE-IVD mark, which is based on a combination of the methylation analyses of SHOX2 and PTGER4 (the prostaglandin E receptor 4 gene)." (PMID 31316555, 2019). "Similar conditions in the validation group, i.e., significantly increased methylation levels of PTGER4 and elevated levels of IDH1, were observed in lung cancer patients compared with healthy controls (p < 0.05)." (PMID 31888670, 2019). "DNA methylation analysis of SHOX2 combined with PTGER4 in blood plasma allows detection of lung cancer and differentiation of non-malignant diseases." (PMID 39132504, 2024). "Therefore, the DNA methylation of the SHOX2 gene has been qualified as a sensitive biomarker for lung cancer diagnosis and staging, specifically for SCC and SCLC, accompanied by an analysis of the methylation level of PTGER4 in our study." (PMID 31888670, 2019).
colitis (28 papers, 2009 to 2025). Inflammation of the colon. "Ptger4, which is related to colitis and hearing loss, is also expressed in intestine tissue." (PMID 25790447, 2015). "In the context of our animal model of defining a biological fingerprint post-resolution of TNBS-induced colitis, the identification of PTGER4 is particularly exciting." (PMID 39456204, 2024). "The finding of PTGER4 as an important CD target gene in the 5p13.1 region is also in line with reports of Ptger4 knock-out mice developing severe DSS-induced colitis." (PMID 23300802, 2012). "CD-associated alleles have recently been negatively correlated to quantitative expression levels of prostaglandin receptor EP4 (PTGER4) and PTGER4 knockout mice experience more severe colitis in the dextran sodium sulfate model of colitis." (PMID 19636438, 2009). "Beyond the Hippo pathway, the prostaglandin E (PGE) signaling pathway enhances YAP1 expression and activity, upregulating cyclocyception 2 and prostaglandin E receptor 4 (EP4), stimulating colon cancer cell proliferation and colon tissue regeneration in colitis mice." (PMID 40066231, 2025). "Since Ptger4−/− mice develop severe dextran sodium sulphate (DSS)-induced colitis while treatment with EP4-selective agonists has protective effects against colitis through enhancement of epithelium survival and regeneration, PTGER4 represents an attractive IBD candidate gene." (PMID 23300802, 2012).
colorectal cancer (21 papers, 2011 to 2025). A primary or metastatic malignant neoplasm that affects the colon or rectum. "Studies have shown that PTGER4 is involved in the growth and development of carcinomas, including colorectal cancer." (PMID 37670284, 2023). "Indeed, PTGER4 has been demonstrated to promote human lung and colorectal cancer cell growth." (PMID 21589857, 2011).
colon carcinoma (20 papers, 2008 to 2025). "In contrast, the average expression level of PTGER4 of group 1 of colon cancer samples is lower than that of group 2 of colon cancer samples or normal samples." (PMID 31856825, 2019).
gastric cancer (17 papers, 2013 to 2025). A primary or metastatic malignant neoplasm involving the stomach. "PTGER4 SNPs might affect the susceptibility to gastric cancer." (PMID 41284374, 2025). "PTGER4 is a major prostaglandin E2 (PGE2) receptor whose genetic variation and expression levels can affect gastric cancer." (PMID 39445005, 2024). "The PTGER4 protein, one of the G-protein-coupled receptor subtypes of PGE2, inhibits growth of human gastric carcinoma cell lines and plays an important role in the inflammatory response caused by H. pylori." (PMID 24069371, 2013).
Crohn disease (15 papers, 2011 to 2024). A gastrointestinal disorder characterized by chronic inflammation involving all layers of the intestinal wall, noncaseating granulomas affecting the intestinal wall and regional lymph nodes, and transmural fibrosis. "An intergenic region was the fourth non-MHC locus, with the closest gene to the lead SNP encoding the prostaglandin E receptor 4 (PTGER4) and pheWAS revealing this SNP as strongly associated with Crohn’s disease and allergic rhinitis." (PMID 35768473, 2022). "Fasting responsive genes were also regulated by variants associated to Crohn’s disease (PTGER4), Rheumatoid arthritis (PHLDB1), Lung Function (ADAM19) and with cardiac troponin (TNNT2)." (PMID 30193568, 2018). "For example, it has been shown for Crohn's disease that disease-associated alleles in a gene-desert region in 5p13.1 correlate with expression levels of PTGER4, the closest gene to this region." (PMID 27708579, 2016). "Two polymorphisms in PTGER4 (rs4495224 and rs7720838) have been associated with susceptibility to Crohn's disease in three independent cohorts." (PMID 27708579, 2016). "Genome-wide association studies identified a PTGER4 expression-modulating region on chromosome 5p13.1 as Crohn's disease (CD) susceptibility region." (PMID 23300802, 2012). "Similarly, gene polymorphisms in PTGER4 loci are associated with increased PTGER4 gene expression and susceptibility to Crohn disease, suggesting a critical role of EP4 receptors." (PMID 32962984, 2020). "Notably, the association of PTGER4 rs7720838 with Crohn's disease has recently been replicated in other populations." (PMID 27708579, 2016). "For example, PTGER4 rs7720838 was found associated with the risk of Crohn's disease." (PMID 22685595, 2012). "Joint analysis of disease GWAS and eGWAS identified potential candidate genes for asthma (ORMDL3), Crohn's disease (PTGER4), NIDDM (PHACS), thalassemia (HBS1L). eGWAS is a useful approach to detect disease SNPs with a functional role." (PMID 21569597, 2011).
prostate carcinoma (15 papers, 2011 to 2025). A carcinoma that arises from epithelial cells of the prostate gland. "EP4 (PTGER4), expressed in epithelial and immune cells, modulates the prostate cancer immune microenvironment." (PMID 40034825, 2025). "The expression of S100P in the colon is mediated by prostaglandin E2 (PGE2)–prostaglandin E receptor 4 (PTGER4) signaling, in prostate cancer by IL-6, and in breast and cervical by glucocorticoids." (PMID 33005177, 2020). "Many of the immune response related (e.g., IRF8, JAK3, PTGER4, RELB, IFITM3) and part of the lipid metabolism related genes (e.g., NR1H4, PPARGC1B, PLIN1, HSD17B14) were identified to be adaptive which addressed their significance for prostate cancer." (PMID 36809527, 2023).
cervical carcinoma (12 papers, 2012 to 2021). A carcinoma arising from either the exocervical squamous epithelium or the endocervical glandular epithelium. "We have previously shown that PTGS1, PTGS2, PTGER2 and PTGER4 are elevated in cervical cancers." (PMID 22442729, 2012). "Our laboratory and others have demonstrated elevated expression of PTGS1, PTGS2, the E-series prostanoid receptors PTGER2 and PTGER4 together with enhanced biosynthesis and signaling of PGE2 in cervical carcinomas." (PMID 22442729, 2012).
asthma (11 papers, 2011 to 2025). "In contrast, single nucleotide polymorphisms (SNPs) of prostaglandin E4 receptor (PTGER4) are reported to be associated with asthma symptoms." (PMID 30192865, 2018). "Recently, PTGER4 polymorphisms have been found to be associated with asthma including aspirin-intolerant asthma, suggesting a role also in inflammation of the respiratory tract." (PMID 23300802, 2012). "S1P induced the expression of some asthma-related genes, such as ADRB2, PTGER4, and CCL20, in the bronchial epithelial cells." (PMID 30192865, 2018). "Therefore, ADRB2 and PTGER4 may contribute to the S1P-induced experimental asthma mouse model." (PMID 30192865, 2018). "Similarly, expression of the prostaglandin receptor PTGER4 in the lung might be impacted by common deletions of JUND and SP1 binding sites (MAF = 14.2%), which might have important roles in the modulation of prostaglandins in allergic pulmonary inflammation and asthma." (PMID 37684227, 2023).